GNAO1 (G protein subunit alpha o1)
Diseases named in the same sentence as GNAO1 in open-access papers (continued):
Sharing a sentence is not in itself a finding about the gene and the disease.
Encephalopathy (continued). "This discovery was followed by an avalanche of clinical analyses that cumulatively led to the recognition of GNAO1 encephalopathy as a spectrum of neurodevelopmental disorders manifesting as motor dysfunction, epileptic seizures, and developmental delay first appearing mostly in infancy." (PMID 36206333, 2022). "To establish a GNAO1 encephalopathy model in the fruit fly, we applied the CRISPR-Cas9 mutagenesis together with phiC31-mediated recombinase-mediated cassette exchange (RMCE) to introduce the pathogenic G203R mutation into the Drosophila Gαo (see Materials and Methods and fig." (PMID 36206333, 2022). "These recovery effectiveness in cells prompted us to next ask whether zinc can be effective at a higher level of complexity, i.e., in an organism model of GNAO1 encephalopathy." (PMID 36206333, 2022). "Given the large body of clinical evidence on the dietary zinc supplements for human patients with diverse neurological conditions, our findings may speak for the applicability of such supplementation for the patients with pediatric GNAO1 encephalopathy." (PMID 36206333, 2022). "In a broader sense, it has been unknown if (and to which extent) GNAO1 encephalopathy is a neurodevelopmental disorder." (PMID 35090564, 2022). "This drug has been shown to be effective in some patients with GNAO1-encephalopathy." (PMID 35090564, 2022). "Brain MRIs are usually normal in GNAO1-related encephalopathies, and the discovery of a PVNH might be coincidental (although we cannot exclude a possible link with the genetic variant); that needs to be confirmed with further studies." (PMID 34685729, 2021). "The number of GNAO1-encephalopathy cases increases steadily since 2013, and it is clear that this rare neurological disease currently suffers from underdiagnosis due to the inaccessibility of whole-genome/exome or even targeted sequencing to many pediatric centers worldwide." (PMID 34685729, 2021). "Three familial cases were already reported in spite of a small number of total patients, which suggested parental mosaicism might be common in GNAO1 encephalopathy." (PMID 33298085, 2020). "Including the present report, twelve patients with GNAO1 encephalopathy have been described." (PMID 27072799, 2016). "With this observation, a total of twelve patients with GNAO1 encephalopathy have been reported." (PMID 27072799, 2016). "Similarly, in the Drosophila model of GNAO1 encephalopathy, GαoG203R/GαoG203R homozygous mutant flies die at the second larval stage, later than the Gαo−/− null animals that do not survive past the embryonic stage, also suggesting the partial LOF genetics of the mutation." (PMID 40745211, 2025). "In summary, our work sheds light on the molecular etiology of GNAO1 encephalopathy, identifies the neomorphic intermediates of the disease dominance, provides a much-needed biomarker for assessment of disease severity, and might pave the way for future drug discovery for this disorder." (PMID 38874642, 2024). "Thus, our work unveils GNAO1 encephalopathy as to a large extent neurodevelopmental malady." (PMID 35090564, 2022). "Our work sheds light on the basic functions of the major neuronal G protein and on the molecular etiology of GNAO1 encephalopathy and might serve as grounds for recommendation of the dietary zinc supplementation as a treatment option for patients with GNAO1 encephalopathy." (PMID 36206333, 2022). "Different functional alteration may contribute to different phenotypes of GNAO1 encephalopathy." (PMID 33298085, 2020). "Determining the genetic processes by which GNAO1 variations impact locomotor activity is made possible by the power of the C. elegans model system, which may also hold the key to resolving unresolved mechanistic questions about the molecular basis of GNAO1 encephalopathy." (PMID 40771566, 2025).
Encephalopathy (continued). "We show that, unlike other previously characterized encephalopathy variants, mutations in the Gln52 result in a loss of basic biochemical and cellular activities of the Gα-subunits, providing a novel basis for the molecular etiology of the GNAO1- and GNAI1-related pediatric encephalopathies." (PMID 34685729, 2021). "As of today, no curative therapy exists for GNAO1 encephalopathy patients, with symptomatic treatments at best demonstrating partial and temporary effects." (PMID 35090564, 2022). "Adequate animal models to study the molecular aetiology of GNAO1 encephalopathies have also so far been lacking." (PMID 33036271, 2020). "No curative therapy exists for patients with GNAO1 encephalopathy." (PMID 36206333, 2022). "We wish to underline that the incompetence to interact with guanine nucleotides we ascribe to the Gln52 mutations in GNAO1 and GNAI1 is unlikely to be the general molecular feature for all the >30 point mutations identified in either gene in the pediatric encephalopathy patients." (PMID 34685729, 2021). "Language impairment can be profound, especially in GNAO1 and GNB1 encephalopathy, and it is not clear if it is related to the prominent oromandibular distribution of movement disorders, or if it depends on cognitive impairment with or without oral dyspraxia." (PMID 36003298, 2022).
Intellectual disability (16 papers, 2017 to 2026). "Among them, the p.Thr327Arg variant in GNAO1, encoding the major neuronal G protein Gαo, was identified in one patient diagnosed with CAS and intellectual disability (ID)." (PMID 41387899, 2025).
breast carcinoma (7 papers, 2012 to 2024). "Using this technique, Kan and colleagues identified an uncharacterized somatic mutation in GNAO1 from breast carcinoma tissue." (PMID 26894955, 2016). "An activating R234H mutation in the guanine nucleotide-binding protein G(o) subunit alpha (GNAO1) has been implicated in breast cancer." (PMID 23365759, 2013). "Kan and colleagues utilized mismatch repair detection (MRD) technology to identify somatic mutations in primary human tumor samples and identified a previously uncharacterized arginine 243 to histidine (R243H) mutation in the G-protein α subunit GNAO1 in breast carcinoma tissue." (PMID 26894955, 2016). "According to Kaplan Meier plot of six aberrantly methylated genes in tissue, low expression of GNAO1 correlated with breast cancer." (PMID 31569550, 2019). "Meanwhile, some research has shown that GNAO1 also plays a significant role in breast cancer and hepatocellular carcinoma." (PMID 28302149, 2017). "“GNAO1 (Gαo) gene was identified in breast carcinomas and shown to promote oncogenic transformation when introduced into cells”." (PMID 23216862, 2012). "In particular, we identified JUN, FADD, NFKB1, Bcl-2, GNAO1, and MMP14 as potential targets of EGCG in breast cancer." (PMID 28713815, 2017). "Several nodes in this pathway emerged as potential direct targets of EGCG in breast cancer: JUN, FADD, NFKB1, Bcl-2, GNAO1, and MMP14." (PMID 28713815, 2017). "The results suggest that signaling proteins affected by EGCG in breast cancer, which include JUN, FADD, NFKB1, Bcl-2, GNAO1, and MMP14, are involved primarily in cell death and survival; DNA replication, recombination and repair; and the cell cycle." (PMID 28713815, 2017). "Additionally, our study explored the roles of other hub genes, including BCL2, PLCB1, ADCY1, and GNAO1, within the HER2-positive breast cancer context." (PMID 39682150, 2024). "Our network analysis also allowed us to identify several specific proteins that EGCG may help regulate in breast cancer, including JUN, FADD, NFKB1, Bcl-2, GNAO1, and MMP14." (PMID 28713815, 2017).
Chorea (7 papers, 2018 to 2025). Chorea (Greek for 'dance') refers to widespread arrhythmic involuntary movements of a forcible, jerky and restless fashion. "In the remaining patients, gait dystonia was associated with chorea (ATP1A3, GNAO1, and NKX2." (PMID 36054588, 2022). "For GNAO1-related disorders, tetrabenazine, in particular in combination with neuroleptics (risperidone, haloperidol), appears to be effective for the baseline treatment of chorea." (PMID 29948482, 2018). "Indeed, ADCY5- and PDE10A-related disorders seem to show a static or mildly progressive course, while GNAO1-related movement disorders are characterized by progressive chorea which can become life-threatening in some patients." (PMID 29948482, 2018).
Ohtahara syndrome (7 papers, 2020 to 2025). "DEE, described in the literature as Ohtahara syndrome, infantile spasms, or EIFMS can be the epileptic presentation of GNAO1, GNB1, and PDE2A." (PMID 36003298, 2022).
developmental and epileptic encephalopathy (6 papers, 2021 to 2025). An epilepsy associated with developmental impairment that may be due to either the underlying etiology or the superimposed epileptic activity, or both. "We also show that common GNAO1 developmental epileptic encephalopathy variants cannot adopt the fully activated conformation required for Gαo-GTP binding to Rap1GAP1a." (PMID 40615045, 2025).
hepatocellular carcinoma (6 papers, 2013 to 2022). A malignant tumor that arises from hepatocytes. "GNAO1, the alpha O1 subunit of G protein, was reported to be significantly downregulated in hepatocellular carcinoma (HCC), as well as being implicated in a variety of intracellular biological events; findings suggest that it may act as a tumor suppressor." (PMID 34900204, 2021). "Another previous study reported that GNAO1 is able to reduce cell proliferation and induce senescence in human hepatocellular carcinoma (HCC)." (PMID 31569550, 2019).
Dyskinesia (5 papers, 2022 to 2025). A movement disorder which consists of effects including diminished voluntary movements and the presence of involuntary movements. "In conclusion, ADCY5 variants are characterized by nocturnal dyskinesia, which improves with caffeine, while GNAO1-related disorders usually present with dystonic storms." (PMID 40724495, 2025). "GNAO1 variants lead to reduced inhibition of its mediated Ca2+ currents resulting in seizures or dyskinesia." (PMID 40826482, 2025). "Overall, these findings deepen our understanding of the disease mechanisms and provide more evidence for caffeine’s potential efficacy in managing dyskinesia linked to GNAO1 loss-of-function mutations." (PMID 40771566, 2025). "Overall, our findings provide new insights into disease mechanisms and further support the potential efficacy of caffeine in controlling dyskinesia associated with pathogenic GNAO1 mutations." (PMID 36833246, 2023). "Beyond the classic presentation, some patients with GNAO1 variants may exhibit a dystonic–dyskinetic status, characterized by the exacerbation of fluctuating and often combined movement disorders, including chorea, dystonia, athetosis, ballism, dyskinesia, and myoclonus." (PMID 40724495, 2025). "Our findings also reveal the potential role of caffeine and other AR antagonists in controlling GNAO1-related dyskinesia." (PMID 34622282, 2022). "On this basis, a clear assessment of the direction of the alteration of cAMP (increase vs. decrease) resulting from different GNAO1 mutations is crucial for establishing inclusion and exclusion criteria in clinical trials with caffeine in GNAO1-related dyskinesia." (PMID 36833246, 2023). "Overall, our findings establish a suitable platform for drug discovery, which may assist in accelerating the development of new therapies for this devastating condition, and highlight the potential role of caffeine in controlling GNAO1-related dyskinesia." (PMID 34622282, 2022).
Epileptic seizures (4 papers, 2016 to 2022). "De novo heterozygous mutations in the GNAO1 gene, encoding the Gα o subunit of G-proteins, are the cause of a severe neurodevelopmental disorder, featuring early infantile seizures, profound cognitive dysfunction and, occasionally, movement disorder (early infantile epileptic encephalopathy-17)." (PMID 27072799, 2016).
gastric cancer (4 papers, 2017 to 2024). A primary or metastatic malignant neoplasm involving the stomach. "Their findings also demonstrated that knockdown of GNAO1 leads to reduced proliferation and promotes the apoptosis of gastric cancer cells." (PMID 30987631, 2019). "The silencing of GNAO1 in gastric cancer cells inhibits cell proliferation and enhances cell apoptosis; increased GNAO1 predicts the unfavorable prognosis in patients with gastric cancer." (PMID 28350845, 2017). "Nevertheless, GNAO1 functions as tumor driver in gastric cancer." (PMID 28350845, 2017). "Gene GNAO1 was found to be overexpressed in 62.9% of patients with gastric cancer, while in our CRC tissue samples gene GNAO1 was down-regulated." (PMID 30987631, 2019).
microcephaly (4 papers, 2020 to 2022). A congenital or acquired developmental disorder in which the circumference of the head is smaller than normal for the person's age and sex.
Parkinsonism (4 papers, 2022 to 2025). Characteristic neurologic anomaly resulting from degeneration of dopamine-generating cells in the substantia nigra, a region of the midbrain, characterized clinically by shaking, rigidity, slowness of movement and difficulty with walking and gait. "Along the same line, we recently showed that 2 GNAO1 mutations affecting the N-terminus of Gαo — L13P and L23P — lose Gβγ binding without acquiring the neomorphic Ric8 interaction, in agreement with their association with a mild parkinsonism phenotype." (PMID 38874642, 2024). "More recent pathogenic GNAO1 variants leading to loss-of-function (LOF) and haploinsufficiency have been associated with milder phenotypes such as adolescent/adult-onset non-progressive dystonia, parkinsonism, and autism." (PMID 40745211, 2025).
schizophrenia (4 papers, 2013 to 2024). A major psychotic disorder characterized by abnormalities in the perception or expression of reality. "Additionally, missense mutations and downregulation of GNAO1 in lymphocytes occur in individuals with schizophrenia." (PMID 31673306, 2019). "Interestingly, GNAO1 is associated with schizophrenia and depression." (PMID 40051599, 2024). "However, a follow-up study failed to report changes in NRG1, DTNBP1, or GNAO1 in patients with schizophrenia vs. controls." (PMID 23805071, 2013).
Onset (3 papers, 2022 to 2026). The age group in which disease manifestations appear.
cerebral palsy (2 papers, 2023 to 2025). A group of disorders affecting the development of movement and posture, often accompanied by disturbances of sensation, perception, cognition, and behavior. "This condition has been documented in cerebral palsy, and it can be hypothesized that it could cause stridor in GNAO1-RD." (PMID 41153036, 2025).
glioma (2 papers, 2014 to 2024). A benign or malignant brain and spinal cord tumor that arises from glial cells (astrocytes, oligodendrocytes, ependymal cells). "Although never described in glioma studies, EFEMP2, and GNAO1 are reported in pathway databases to be also involved with phospholipase-C (PLC) activity." (PMID 38812741, 2024).
heart failure (2 papers, 2022 to 2024). Inability of the heart to pump blood at an adequate rate to meet tissue metabolic requirements. "GNAO1, which was downregulated by REST, has been reported recently to be a therapeutic target of heart failure." (PMID 39377066, 2024).
infantile spasms (2 papers, 2022 to 2023). A rare epilepsy syndrome characterized by onset of epileptic spasms in infants between 2 and 12 months of age, and rarely up to 24 months. "Onset with tonic seizures or infantile spasms with EEG patterns of burst suppression or hypsarrhythmia has been described for GNAO1 and GNB1." (PMID 36003298, 2022).
liver cancer (2 papers, 2011 to 2021). An epithelial or non-epithelial malignant neoplasm that arises from the liver.
AADC deficiency (1 paper, 2022). "1‐, and GNAO1‐related HMD, as well as AADC deficiency and DTDS." (PMID 36054588, 2022).
alcohol addiction (1 paper, 2025). "GNAO1, a G protein subunit alpha o1, mediates the function of various neuronal receptors, including those implicated in alcohol addiction." (PMID 40124499, 2025).
autonomic dysfunction (1 paper, 2018). "Distinguishing clinical features may further include sleep-related phenomena and marked fluctuation in ADCY5 disease, abnormal MRI features in dominant PDE10A disease, and severe exacerbations associated with autonomic dysfunction in patients with GNAO1 mutations." (PMID 29948482, 2018).
demyelinating disease (1 paper, 2024). A broad group of disorders that affect the myelin sheaths that cover the neurons. "Typically, seizures and movement disorders are the frequent symptoms in demyelinating diseases, such as MS, we thus hypothesized that there must be a correlation between Gnao1 and myelination." (PMID 38331815, 2024). "In light of the current data, our findings uncover a function of Gnao1 to negatively regulate SC differentiation, identifying a novel candidate drug target for the treatment of demyelinating diseases." (PMID 38331815, 2024). "Taken together, our data indicate that Gnao1 negatively regulated SC differentiation by reducing cAMP level and inhibiting PI3K-AKT cascade activation, identifying a novel drug target for the treatment of demyelinating diseases." (PMID 38331815, 2024).
Dravet syndrome (1 paper, 2025). "Eight individuals (6.2%) had died after their last follow-up; four had SCN1A-related Dravet syndrome; the others had CHD2, GNAO1, KCNT1 and NEXMIF-related DEEs." (PMID 39882024, 2025).
endothelial dysfunction (1 paper, 2024). In vascular diseases, endothelial dysfunction is a systemic pathological state of the endothelium (the inner lining of blood vessels) and can be broadly defined as an imbalance between vasodilating and vasoconstricting substances produced by (or acting on) the endothelium. "We also found dysregulation of angiogenesis genes (XDH, SEMA5A, and SULF1) and the Rap1 pathway (ADORA2B, GNAO1, SULF1, and EFNA2), which promotes endothelial homeostasis and may be involved in endothelial dysfunction-associated cardiovascular pathologies." (PMID 38255763, 2024).
ependymal tumor (1 paper, 2020). A group of neoplasms which arise from the ependymal lining of the cerebral ventricles and from the remnants of the central canal of the spinal cord.